EPHB6 (EPH receptor B6)
Description:
Kinase-defective receptor for members of the ephrin-B family. Binds to ephrin-B1 and ephrin-B2. Modulates cell adhesion and migration by exerting both positive and negative effects upon stimulation with ephrin-B2. Inhibits JNK activation, T-cell receptor-induced IL-2 secretion and CD25 expression upon stimulation with ephrin-B2. Can recruit SH2 domain-containing signaling adapters following phosphorylation by EPHB4.
Synonyms: HEP
Target class: Membrane receptor
Gene: Protein-coding gene on chromosome 7 (142,854,930 to 142,871,094, forward strand). Ensembl gene ENSG00000106123.
Subcellular location: Cell membrane; Secreted (Isoform 3)
Subcellular location (Human Protein Atlas): Nuclear speckles
Pathways (Reactome):
Developmental Biology: EPH-Ephrin signaling; EPH-ephrin mediated repulsion of cells; EPHB-mediated forward signaling; Ephrin signaling
Genetic constraint (gnomAD): Loss-of-function variants: 53 observed, 109.85 expected, observed/expected ratio (o/e) 0.48, 90% interval 0.39 to 0.61. The upper end of that interval is the gene's LOEUF score, 0.61, which puts it in group 2 of 6, group 1 being the genes least tolerant of losing a copy. Missense variants: 1,141 observed, 1,401.1 expected, observed/expected ratio (o/e) 0.81, 90% interval 0.77 to 0.86. Synonymous variants: 553 observed, 574.77 expected, observed/expected ratio (o/e) 0.96, 90% interval 0.9 to 1.03.
Homologues: Orthologues: chimpanzee EPHB6 (99% identical), macaque EPHB6 (99% identical), rabbit EPHB6 (92% identical), dog EPHB6 (92% identical), guinea pig EPHB6 (92% identical), mouse Ephb6 (92% identical), rat Ephb6 (91% identical), pig EPHB6 (90% identical). Paralogues in human: LMTK2 (17% identical), EPHB2 (9% identical), EPHB1 (8% identical), EPHB3 (8% identical), EPHA4 (8% identical), EPHA5 (8% identical), EPHA8 (8% identical), EPHA3 (8% identical), EPHA7 (8% identical), EPHB4 (8% identical), KDR (8% identical), EPHA1 (8% identical), and 41 more.
Diseases named in the same sentence as EPHB6 in open-access papers:
EPHB6 is named in the same sentence as 83 diseases in open-access papers, as found by Europe PMC text mining. Sharing a sentence is not in itself a finding about the gene and the disease. The quoted sentences say what the papers report.
breast carcinoma (28 papers, 2010 to 2025). "Overall, these observations identified SRC as a molecule of choice for targeting EPHB6-deficient breast cancer cells." (PMID 27418135, 2016). "There are also several genes close to this region that are associated with many types of cancer including breast cancer, EPH receptor B6 (EPHB) and Transient receptor potential vanilloid 6 (TRPV6)." (PMID 25423363, 2014). "In breast cancer, low EphB6 expression is linked to enhanced tumor invasiveness; treatment of aggressive breast cancer cell lines with 5’-aza-2’-deoxycytidine elevates EphB6 expression and to reduces tumor cell invasiveness." (PMID 33962392, 2021). "Others, however, have linked EphB6 to increased tumor growth in breast cancer." (PMID 34943502, 2021). "It is noteworthy that while EphB6 has been considered a tumor suppressor in cell line models of breast tumorigenesis, its association with reduced survival in breast cancer patients has also been reported." (PMID 29682554, 2018). "While a large body of evidence supports the idea that DRP1-mediated mitochondrial fission is pro-tumorigenic in nature, including in breast cancer, our findings clearly indicate that EPHB6-positive tumour cells should be more susceptible to DR5-activating therapeutic approaches." (PMID 27788485, 2016). "While several other studies reported EphB6 promoter methylation and a tumor suppressor function, our data revealed a significant association between elevated ephB6 and poorer overall and recurrence-free survival in breast cancer." (PMID 21935409, 2011). "The biological significance of these changes may be explained by associating specific consequences of EphB6 protein with its abundance as well as the levels of other Eph receptors in breast carcinoma cells." (PMID 21811619, 2011). "Furthermore, the strong association between EphB6 and ephrinB1 leads to a reduction in the invasiveness of the breast cancer cell line, MDA-MB-231, revealing how EphB6 might function as a tumor suppressor when interacting with ephrinB1 in trans." (PMID 38627519, 2024). "EphB6 has been noted the contribution of oncogenic role in various cancer types, including lung, colon, and breast cancers." (PMID 40065768, 2025). "Lastly, we conducted three-dimensional tumor spheroid assays, which demonstrated that co-clustering of EphB6 and ephrinB1 decreases the invasiveness of the breast cancer cell line, MDA-MB-231." (PMID 38627519, 2024). "In the past, a number of studies have revealed the deregulation of EPHB6 in a variety of malignancies, including breast cancers, colorectal cancers and pediatric T-cell acute lymphoblastic leukemia, among others." (PMID 37101747, 2023). "In invasive breast carcinoma cells, EphB6 expression was found to be transcriptionally silenced by promoter hypermethylation, and it has, therefore, been proposed as a biomarker for breast cancer detection and diagnosis." (PMID 33430066, 2021). "EphB6 depletion is accompanied by reduced TFEB-dependent genes transcription in indolent breast cancer cells from lungs and lung-organotypic system and decreased cytoplasmic area with Lysotracker-positive organelles in mouse and human models of DDCCs." (PMID 33802447, 2021). "EphB6 signaling, known to suppress breast cancer cell aggressiveness by interacting with EPHB4 and interfering with EPHB4 action, was repressed by Pparγ1 in ErbB2 mammary tumors." (PMID 33946495, 2021). "Examples of EphB6 effects on biological cellular responses include the inhibition of EphA2-mediated anoikis resistance in breast cancer cells by preventing Akt-mediated phosphorylation of the EphA2 receptor on Ser897." (PMID 34360976, 2021). "Our work suggests that EphB6 plays a critical role in the crosstalk of indolent breast cancer cells with alveolar type I cells and supports the survival of DDCCs in vivo and in vitro." (PMID 33802447, 2021).
breast carcinoma (continued). "While EPHB6 expression is reduced in invasive breast cancer cell lines, little is known about EPHB6 behaviour in breast cancer tumours." (PMID 29700392, 2018). "Molecular and phenotypical changes in breast cancer cells appear to involve EphB6 cross-talk with cadherin 17, and altered expression of EphB6 influences WNT pathway." (PMID 29682554, 2018). "Consistent with this, our analysis revealed a positive correlation between EPHB6 expression and the long-term recurrence-free survival of breast cancer patients with basal-like tumours that mostly represent TNBC." (PMID 29700392, 2018). "Our investigation revealed that EPHB6 abundance is significantly reduced in breast cancer, which expanded on previous observations that relied solely on breast cancer cell lines." (PMID 29700392, 2018). "The genes PRSS1, TRPV5 and PIP have so far been implicated in a few cancer types (pancreatic-, non-small cell lung- and breast cancer), while EphB6 and TRPV6 have been studied in relation to numerous cancer types." (PMID 29299148, 2017). "Our assessment of TCGA data for immunohistochemistry-based breast cancer subtype classification revealed that EPHB6 is also significantly downregulated in patient samples, representing very heterogeneous and aggressive tumours of the TNBC group." (PMID 27418135, 2016). "Especially the EPHB6, which seems to be coupled to invasion upon re-expression in breast cancer cell lines and to adverse prognosis in breast cancer although the EPHB6 gene seems to be methylated in cancer." (PMID 26870995, 2016). "This agrees well with the previously reported EPHB6 ability to suppress metastasis in non-small cell lung cancer and melanoma, and our own findings that EPHB6 actively reduces breast cancer invasiveness." (PMID 27418135, 2016). "Functionally, EPHB6 suppresses invasiveness, growth rate and colony-forming efficiency of cultured breast cancer cells, regulates cell adhesion and affects migration." (PMID 23226491, 2012). "The transcription of EphB6 is silenced in breast carcinoma cells and its re-expression leads to decreased invasiveness of MDA-MB-231 cells." (PMID 21811619, 2011). "These analyses confirmed the relevance of EphA2 and EphB4 to human breast cancer progression, and uncovered significant correlations for EphA4, EphA7, and EphB6, which were previously under-investigated in breast cancer." (PMID 21935409, 2011). "One of the most deleted genes was EPHB6 that is known to slow breast cancer cell lines invasiveness." (PMID 20126641, 2010). "Also, in molecular level analysis, EphB6 suppresses EphA2-promoted anoikis of breast cancer cells by interfering with EphA2-Ephexin 4 interaction." (PMID 40065768, 2025). "EphB6 supports the survival of dormant breast cancer cells in the lung." (PMID 38457510, 2024). "Interestingly though, despite its anti-invasive properties, EphB6 was found to promote tumor initiation in breast cancer xenografts and in a colorectal cancer model." (PMID 38341842, 2024). "Consistent with this oncogenic potential of EphB6, its expression was positively correlated with tumor size and recurrence rate of malignant thyroid lesions and was also coupled to poor outcome in breast cancer and tongue squamous cell carcinoma." (PMID 38341842, 2024). "The protein EPHB6 is deleted in more aggressive breast cancers, melanomas, and neuroblastomas." (PMID 37101747, 2023). "Next, we investigated the link between the EphB6-dependent gene program and human breast cancer." (PMID 33802447, 2021). "Notably, EPHB6 was also found upregulated in breast cancer cells from metastases compared to estrogen receptor-positive primary breast cancers." (PMID 33802447, 2021). "An additional feature pointing to a role for EphB6 in the communication between lung epithelial cells and DDCCs was the observation that Ephb6 mRNA was upregulated in lung-disseminated DDCCs compared to culture on plastic in indolent breast cancer cells." (PMID 33802447, 2021).
breast carcinoma (continued). "However, more recently EphB6 has been shown to promote aggressive traits, such as increased tumor-initiating capacity of breast cancer cells." (PMID 33802447, 2021). "Interestingly, while attention on EphB6 expression has been focused primarily on primary tumor samples, our analysis shows that EPHB6 mRNA is upregulated in metastatic compared to primary lesions in estrogen-positive breast cancer patients." (PMID 33802447, 2021). "Moreover, a recent study has suggested that the pro-survival effects of EphB6 on disseminated dormant estrogen receptor-positive breast cancer cells can be mediated by inhibition of the GSK3β pathway." (PMID 34360976, 2021). "We then asked whether EphB6 expression in breast cancer cells could influence gene expression in AT1-like cells." (PMID 33802447, 2021). "EphB6 also reduces motility and invasion of breast and lung cancer cells and partially reverses epithelial-to-mesenchymal transition traits of breast cancer cells." (PMID 34360976, 2021). "We tested this hypothesis by assessing Ephb6 expression in indolent breast cancer cells cultivated on substrates with different stiffness." (PMID 33802447, 2021). "Importantly, this effect was phenocopied by depletion of EphB6, highlighting its requirement for the survival of indolent breast cancer cells in a lung microenvironment in vivo and in coculture." (PMID 33802447, 2021). "Interestingly though, despite its anti-invasive properties, EphB6 was also found to promote tumor initiation in breast cancer xenografts and in a colorectal cancer model in the context of Apc mutations." (PMID 34360976, 2021). "Indeed, EPHB6 presence strongly enhanced expression of EpCAM, which was previously characterised as breast cancer TIC marker." (PMID 29700392, 2018). "Given the overexpression of EphA2 in breast cancer cells, tumor suppressor action of EphB6 may be explained by its heteromerization with EphA2." (PMID 29682554, 2018). "While some of these results differ from the previous report, suggesting that EPHB6 expression may be increased in overall breast cancer, this difference is likely a reflection of the smaller database used in the earlier investigation." (PMID 29700392, 2018). "Indeed, analyses of the TCGA and EBI databases reveal that although EPHB6 expression is generally reduced in breast cancer, it is better preserved in TNBC tumours." (PMID 29700392, 2018). "EPHB6 also suppresses metastasis in xenograft models of human lung cancer, melanoma and colorectal cancer, while our previous work indicates that it undergoes tyrosine phosphorylation in breast cancer cells and inhibits breast cancer invasiveness." (PMID 29700392, 2018). "As SRC inhibitors are being actively evaluated in breast cancer clinical trials, our findings strongly suggested that the SL interaction between EPHB6 and SRC might be used to target TNBC tumors." (PMID 27418135, 2016). "Especially EPHA2, EPHA4, EFNB1, EFNB2, EPHB2, and EPHB6 and their co-expression in breast cancer." (PMID 26870995, 2016). "As transcriptional regulation of EPHB6 was suggested to be controlled by promoter methylation in breast cancer cell lines, we analyzed human cancer methylome data and found that EPHB6 is methylated in the promoter region in several malignancies, including breast, colon, lung and prostate tumors." (PMID 27418135, 2016). "Recently, we could demonstrate that EPHB6 is frequently silenced by epigenetic mechanisms in lung cancer, and others could show the same inactivation mechanism in breast cancer." (PMID 23226491, 2012). "We speculate that the decrease in invasiveness of EphB6-expressing breast carcinoma cells may be mediated by miR-16 in a concentration-dependent manner." (PMID 21811619, 2011). "The proteomic alterations observed in EphB6 expressing breast carcinoma cells suggest that changes in the levels of some proteins may be direct effects of EphB6." (PMID 21811619, 2011).
breast carcinoma (continued). "We evaluated protein expression of EphA2, EphA4, EphA7, EphB4, and EphB6 in human breast cancer tissue microarrays (TMA) in which we could distinguish expression in tumor epithelium from stromal components, including endothelium." (PMID 21935409, 2011). "Also, the interaction of EphB6 and EphA2 has been observed in breast cancer cell lines." (PMID 40065768, 2025). "In kidney cancer, the expression of miR-100 is downregulated by PTEN, whereas in breast cancer (BC), it is upregulated by EphB6." (PMID 40161350, 2025). "Investigation of the role of the EPH/ephrin system in breast cancer has mainly focused on the receptors EPHA2, EPHB4, and EPHB6." (PMID 35204461, 2022). "EphB6 has been shown to be consistently downregulated in several types of cancers, such as NSCLC, prostate, ovarian, gastric, breast cancers as well as melanoma and neuroblastoma." (PMID 33802447, 2021). "Among the family members, EPHA2 and EPHB4 are the most studied in breast cancer and additionally EPHA4, EPHA7 and EPHB6 emerged as promising clinical candidates in an expression profile of the individual EPH and ephrin family members." (PMID 26870995, 2016). "Although we found that EPHB2 was the most promising candidate in our breast cancer cohorts, EPHB2 together with EPHB6, EPHA2, EPHA4 and the ligands EFNB1 and EFNB2 were important to define prognostic relevant clusters." (PMID 26870995, 2016). "Their expression in breast cancer has been investigated using cell lines, animal models, and human tissue samples, and correlated with patients’ prognosis EPHA2, EPHB4, and EPHB6 are the receptors most extensively studied so far." (PMID 35204461, 2022). "EphB6, a receptor lacking kinase activity, thereby considered “kinase dead,” has been shown to be downregulated in breast carcinoma cells, suggesting a role as a tumour suppressor." (PMID 33430066, 2021). "Data from our work describe a novel regulator of breast DDCCs survival, EphB6, that modulates adaptation to lung microenvironment through the GSK3β-TFEB-lysosomal axis, providing potential novel liabilities of disseminated dormant breast cancer cells." (PMID 33802447, 2021). "EphB6 expression exists in normal mammary gland and noninvasive breast tumor cell lines, but it is downregulated or absent in invasive metastatic breast cancer cell lines." (PMID 29682554, 2018). "KX2-391 is currently also being tested for breast cancer treatment (NCT01764087) and our finding of the SL relationship between EPHB6 and SRC indicated that KX2-391 treatment may work more efficiently if applied specifically to EPHB6-deficient TNBC cells." (PMID 27418135, 2016). "Interestingly, we did not observe any consistent effect of EPHB6 on the CD24loCD44hi combination, identifying some breast cancer TIC populations and the ALDEFLUOR assay has not revealed a consistent effect on another TIC marker, ALDH1." (PMID 29700392, 2018). "Our observations also reflect an unfortunate reality that there is no universal marker that defines all types of breast cancer TICs and indirectly suggest that EPHB6 itself may serve as a TIC marker in TNBC." (PMID 29700392, 2018). "Our results also suggest that EphB6 may be exploited as a target for therapeutic intervention of breast cancer regardless of the specificity of its downstream effects." (PMID 21811619, 2011). "Interestingly, our previous work showed that the EPHB6 receptor suppresses aggressiveness of breast cancer cells by interacting with EPHB4 and interfering with EPHB4 action, which implies that EPHB6 may also enhance the DR4- or DR5- mediated apoptotic response." (PMID 27788485, 2016). "Consistent with its reported function in breast cancer TICs, OCT4 silencing strongly reduced the expansion of tumourspheres, while not decreasing EPHB6 expression." (PMID 29700392, 2018).